MPO (myeloperoxidase)
Diseases named in the same sentence as MPO in open-access papers (continued):
Sharing a sentence is not in itself a finding about the gene and the disease.
rheumatoid arthritis (continued). "Similar to excessive ROS production, uncontrolled MPO release by PMN involves the risk of tissue damage, which is associated with a negative course of various inflammatory diseases such as rheumatoid arthritis or acute and chronic pneumonia." (PMID 34115923, 2021). "This fact, the small amount of blood necessary for this analysis and the assumption that the innate immune system, neutrophils and MPO may play a bigger role in RA as classically assumed provide further arguments for considering the activity of this enzyme in future studies on rheumatoid arthritis." (PMID 27023113, 2016). "An association between anti-MPO antibodies and ILD in patients with rheumatoid arthritis without comorbid AAV has been reported in a small retrospective analysis, with 3 of 12 (25%) patients with anti-MPO antibodies manifesting ILD compared to 0 of 85 patients without anti-MPO antibodies." (PMID 30764870, 2019).
inflammatory bowel disease (57 papers, 2010 to 2025). A spectrum of small and large bowel inflammatory diseases of unknown etiology. "Cytokines, including IL‐1β, IL‐6, and TNF‐α, are expressed at relatively higher levels in the intestinal tissues of patients with UC, and MPO‐mediated damage is associated with some disorders in people, including inflammatory bowel disease." (PMID 40586619, 2025). "MPO plays an important role in several diseases, particularly those associated with neutrophil-mediated inflammation, such as inflammatory bowel disease." (PMID 39682476, 2024). "Elevated colonic MPO levels and the presence of neutrophil extracellular traps are closely linked to disease severity in patients with inflammatory bowel disease (IBD)." (PMID 40699843, 2025). "Extracellularly generated hypochlorous acid, the main ROS produced by MPO, has been shown to cause severe tissue, cellular, and DNA damage to bystander cells, which propagate disease in models of subacute and ischemic stroke, multiple sclerosis, and inflammatory bowel disease." (PMID 35269694, 2022). "Furthermore, Butyricicoccus are butyrate-producing bacteria associated with decreased intestinal myeloperoxidase, tumor necrosis factor-α and interleukin-12 levels in inflammatory bowel disease rat models, contributing to reduced pro-inflammatory potential in the gut microenvironment." (PMID 35656540, 2022). "Increased salivary MPO levels were more often observed for inflammatory diseases, except patients with inflammatory bowel diseases who were eligible for biologic therapy." (PMID 37569455, 2023). "In inflammatory bowel disease, MMP-1 activity is closely associated with myeloperoxidase (MPO) levels." (PMID 35392084, 2022). "For example, in an active inflammatory bowel disease, fecal MPO levels increase significantly and correlate with disease activity." (PMID 33886672, 2021). "Fermented cabbage-derived LAB (e.g., L. paracasei) inhibit the pro-inflammatory mediators and inflammatory enzymes, including IL-6, TNF, IFN-γ, and myeloperoxidase (MPO), and alleviate inflammatory bowel disease." (PMID 33946303, 2021). "Oxidative stress in inflammatory bowel disease activates inflammatory cells, such as neutrophils, whose myeloperoxidase catalyzes the production of reactive oxygen species." (PMID 34745425, 2021). "It promotes colonic healing in inflammatory bowel disease (IBD) by myeloperoxidase activity suppression at a dose of 10 mg/kg28." (PMID 32409760, 2020). "Intestinal mucosal S100A12 and myeloperoxidase (MPO) are inflammatory biomarkers in humans with inflammatory bowel disease (IBD)." (PMID 29618371, 2018). "PubMed, provided by the United States National Library of Medicine (NLM) at the National Institutes of Health, was utilized with the following search terms: 1) myeloperoxidase (MPO), 2) inflammatory bowel disease (IBD), and 3) neutrophils." (PMID 28286723, 2017). "Increased MPO and granulocyte infiltration are characteristic and also observed in tissues of patients with relapsing inflammatory bowel diseases which are defined as chronic inflammatory diseases." (PMID 24819503, 2014). "In rats with inflammatory bowel disease, intra-rectal honey administration significantly reduced myeloperoxidase (MPO) activity." (PMID 22499188, 2012). "In addition, MPO levels in feces are considered a viable biomarker for assessing inflammatory bowel disease." (PMID 39203378, 2024). "Furthermore, treatment of inflammatory bowel disease (IBD)-induced mice with compound 1 decreased myeloperoxidase activity in colonic extracts and modulated the colon length and serum levels of cytokines such as TNF–α, IFN–γ, IL–6, IL–1β, and IL–10." (PMID 37893090, 2023). "However, elevated MPO concentrations were more commonly found for inflammatory diseases, with the main interesting exception being patients with inflammatory bowel diseases who were eligible for biologic therapy." (PMID 37569455, 2023).
inflammatory bowel disease (continued). "We also assessed for any possible association of intestinal mucosal S100A12 concentrations and MPO activities with histopathological findings, canine inflammatory bowel disease activity index (CIBDAI) scores, clinical outcome, or hypoalbuminemia in dogs with CE." (PMID 29618371, 2018). "Inflammatory Bowel Disease (IBD)‐ In experimental models of colitis, plumbagin decreases myeloperoxidase activity, inhibits inflammatory mediators, and enhances colon histology." (PMID 40842665, 2025). "Concentrations of the neutrophil protein myeloperoxidase are elevated in the feces of individuals with endoscopically active inflammatory bowel disease (IBD)." (PMID 40411448, 2025). "In a mouse model of inflammatory bowel disease (IBD), it has been shown that myeloperoxidase (MPO) level is correlated with the severity of the disease." (PMID 36016953, 2022). "In inflammatory bowel disease (IBD) models, its expression levels are closely correlated with pathological indicators such as myeloperoxidase (MPO) activity, reactive oxygen species (ROS) production, and cell migration." (PMID 41154702, 2025). "The level of myeloperoxidase (MPO), one of the principal enzymes contained in PMN granules and released upon activation is, in stool, a biomarker of inflammatory bowel disease severity." (PMID 35652591, 2022). "However, in inflammatory bowel disease (IBD), which is a precursor to IBD-associated colon cancer, PMN were found to accumulate in large numbers and to release myeloperoxidase (MPO) along with other enzymes." (PMID 35048056, 2021). "In the inflammatory bowel disease (IBD) induced by LPS in human colon mucosal epithelial cells (NCM460), Mor reduced apoptosis, inflammation, and oxidative stress by regulating Bax/Bcl-2, inhibiting TNF-α, IL-1β, IL-6, SOD, MDA, T-AOC, and MPO levels." (PMID 39301568, 2024). "Furthermore, it was discovered that RS2 ingestion helped improve inflammatory bowel disease (IBD) and lower myeloperoxidase activity." (PMID 39272535, 2024). "We previously observed that inflammatory bowel disease (IBD) may compromise oral host defense, as assessed by decreased salivary levels of immunoglobulin A (IgA) and myeloperoxidase (MPO)." (PMID 34947940, 2021). "In addition to SLE, MPO-ANCA has been described at diagnosis in subpopulations of multiple autoimmune and inflammatory diseases to include anti-GBM disease, IgA nephropathy, and inflammatory bowel disease." (PMID 29435367, 2017). "Moreover, CD177 is a glycoprotein that is exclusively expressed on neutrophils, and CD177+ neutrophils release more ROS, MPO, and calprotectin, and produce more NETs than CD177–neutrophils inflammatory bowel diseases (IBD)." (PMID 39935468, 2025).
ischemia (56 papers, 2007 to 2025). A hypoperfusion of the BLOOD through an organ or tissue caused by a PATHOLOGIC CONSTRICTION or obstruction of its BLOOD VESSELS, or an absence of BLOOD CIRCULATION. "Yet, acute events such as atherosclerotic plaque rupture associated with subsequent ischemia must be recognised as potential confounding factors for the interpretation of D-dimer, MPO, as well as the combined score." (PMID 38137627, 2023). "MPO inhibition has been demonstrated to improve ischemia associated cardiac remodeling in animal experiments." (PMID 35410418, 2022). "In summary, MPO has been demonstrated to be significantly over-generated in neutrophils and monocytes in ischemia-associated cardiac injuries." (PMID 35410418, 2022). "During acute inflammation, neutrophils produce ROS, elastase, myeloperoxidase and release neutrophil extracellular traps (NETs) which can damage tissues by their cytotoxicity and can cause ischemia through thrombocytosis." (PMID 33584717, 2020). "Associated with that, the levels of MPO, which is an inflammatory enzyme and known to be expressed during ischemia, have increased for the generation of free radicals to generate the reactive nitrogen species to overwhelm the oxidative damage on the retinal cells." (PMID 32666339, 2020). "Neutrophils are the major mediators to increase the microvascular permeability induced by reperfusion; some authors have reported that the exposure of gastric mucosa to ethanol and ischemia followed by reperfusion caused significant increase in the MPO activity." (PMID 22654592, 2012). "The ischemia caused by repeated forearm arterial and venous occlusions performed during the vascular function tests may have produced brief periods of turbulent flow causing an increase in MPO." (PMID 19624856, 2009). "In a study, the effects of berberine and coenzyme Q10 on hind limb I/R injury were evaluated, and the increased MDA and myeloperoxidase in the ischemia group were reduced by berberine supplementation." (PMID 40142262, 2025). "Histological improvement was most pronounced when APO was administered during ischemia, while significant reductions in MDA and MPO levels, key biochemical markers of oxidative and inflammatory injury, were observed when it was given prior to ischemia." (PMID 40867921, 2025). "Neurobehavioral outcomes, infarct volume, inflammatory cytokines, myeloperoxidase, and tight junction protein levels were measured following ischemia." (PMID 40740844, 2025). "Immunohistochemical data showed that increased myocardial neutrophil infiltration, as evidenced by quantification of MPO-positive cells, in the 5h ischemia hearts compared to the 1h ischemia group, was significantly decreased by preservation with AAT." (PMID 37426668, 2023). "Eugenol (10 mg/kg/day) also reduced MPO hepatic activity in a rat model of hepatic ischemia/reperfusion." (PMID 38256335, 2023). "Ischaemia led to a significant increase in MPO activity and TNF-α, and IL-6 concentrations in the ovaries when compared with the sham-operated animals." (PMID 36200598, 2022). "The myeloperoxidase activity in ipsilateral torsional testes in the testicular ischemia-reperfusion and testicular ischemia-reperfusion+vehicle groups was significantly higher compared with that in the control group (P < 0.05)." (PMID 36388170, 2022). "In a previous study, it was shown inthe murine heart that acute myocardial ischaemia and reperfusion increased myocardialexpression of MPO, but this was attributed to infiltrating leucocytes." (PMID 33705529, 2022). "An animal model of ischemia-related myocardial damage revealed that MPO augments arrhythmogenic left ventricular remodeling and enhanced ventricular post ischemic fibrosis." (PMID 36498593, 2022). "Using an enzyme-activated MRI agent that can track the oxidative activity of MPO, it has been shown that MPO accumulates in large amounts also during ischemia." (PMID 33505588, 2021).
ischemia (continued). "In the present study, we observed increased MPO levels in the spinal cord at 72 h after ischemia compared to that in the control group." (PMID 31683736, 2019). "The results showed that OT significantly reduced heat-induced lung edema, neutrophil infiltration, hemorrhage score, myeloperoxidase activity, ischemia, and the levels of inflammatory and oxidative damage markers in bronchoalveolar lavage fluid." (PMID 31804535, 2019). "In this study, MPO concentrations from lung homogenates in the reperfusion group were much higher than those of the ischemia and sham groups." (PMID 25677043, 2015). "Kallikrein attenuated ischemia-induced apoptosis andmonocyte/macrophage accumulation in the ischemic myocardium, in conjunction withincreased nitric oxide levels and reduced myeloperoxidase activity." (PMID 26351984, 2015). "There were significant differences in MPO activity after 1, 2, and 3 h of ischemia animals compared to sham controls." (PMID 25541714, 2014). "Hemin administration almost completely abolished the ischemia-induced increase in MPO activity, whereas the HO-1 inhibitor ZnPP-IX abolished the hemin protective effects." (PMID 23592614, 2013). "There were limited MPO+ cells in the normal (21.3 ± 1.3) and the ischemia only kidneys (25.2 ± 2.7)." (PMID 24282430, 2013). "Next, we performed a myeloperoxidase (MPO) activity assay to determine the neutrophil influx in the ischemia cerebral cortex." (PMID 22768247, 2012). "The liver MPO levels of both wild-type and P/I null mice after 90 minutes of ischemia followed by 6 and 15 h of reperfusion were significantly elevated compared to the sham-operated mice at the corresponding time points." (PMID 17524141, 2007). "The three distinct rRIPoC procedures reduced the MPO level compared with that with RIPoC procedure at 3 days after ischemia, with 82.3 ± 12.1 μUnit/mg for every half day, 83.8 ± 12.6 μUnit/mg for every 1 day, 112.8 ± 19.1 μUnit/mg for every 2 days (P < 0.05, versus 141.0 ± 22.6 μUnit/mg)." (PMID 28944999, 2018). "The expressions of MDA and MPO in serum and skeletal muscle were significantly higher in reperfusion + postfasciotomy group (group B) and prefasciotomy + reperfusion group (group C) compared with ischemia reperfusion group (group A) (all p < 0.05)." (PMID 28856161, 2017). "Compared with the control group, xanthione peroxidase (XO) and myeloperoxidase (MPO) activity in the vehicle-treated group significantly increased, by 6.154- and 3.326-fold, respectively, 24 h after ischemia/reperfusion, and by 4.265- and 2.986-fold, respectively, 72 h after ischemia/reperfusion." (PMID 28981094, 2017). "Therefore, the activity of MPO in the myocardium of rats was utilized to reflect the infiltration of neutrophils induced by ischemia insult." (PMID 26788242, 2016). "An interesting additional finding from our study is that there is significantly increased MCP1/CCL2 expression and MPO activity in the right lung following left lung ischemia-reperfusion and that this right lung response is attenuated in Myd88-/- and, to a lesser extent Tlr4-/- mice." (PMID 24146959, 2013). "Treatment with alpinetin attenuated the neuroinflammatory cascade by reducing MPO activity, a marker of neutrophil infiltration, and suppressing glial activation in both microglia and astrocytes, which are key contributors to secondary injury following ischemia." (PMID 41373489, 2025). "Furthermore, in a mouse MI model, administration of PF-1355 (MPO inhibitor) for 7 days reduced inflammatory cell infiltration and attenuated left ventricular dilation, and MPO inhibition has been shown to improve ischemia-related cardiac remodeling in animal experiments." (PMID 36761726, 2023). "In addition, compared to the sham group, 1 h of ischemia and different times of reperfusion (2 h, 6 h, and 24 h) significantly increased MPO (p-values = 0.005, 0.004, and 0.009) and LDH (p-values = 1.86 × 10−8, 2.43 × 10−11, and 0.002) levels in serum, respectively." (PMID 27399769, 2016).
ischemia (continued). "Consistently, we found that ischemia-induced TREM-1 promoted IL-1β, IL-18, IL-6, CXCL-2, MCP-1, and CXCL-1 productions in microglia as well as the expression of MPO and ICAM-1 following ischemic injury." (PMID 31324751, 2019). "In the PEP-1 peptide-treated and control-PEBP1-trateed groups, MPO, TNF-α, and HMGB levels were significantly robustly increased in the spinal cord 72 h after ischemia compared to those in the control group." (PMID 31683736, 2019). "During myocardial ischaemia-reperfusion injury, L-THP administration significantly decreased the accumulation of inflammatory factors, including TNF-α and MPO." (PMID 26819501, 2015). "The increased myeloperoxidase (MPO) activity and expression of TNF-α, iNOS, and glial fibrillary acidic protein (GFAP) during ischemia could also be abrogated by eriodictyol." (PMID 31814878, 2019). "On the other hand, the MPO activity in the cortex that was increased during ischemia was enhanced in the DM group relative to that in the non-DM group." (PMID 26665003, 2015). "Additionally, we showed that it significantly improved post ischemia brachial artery diameter and FMD, an effect which was independent of the reduction in plasma lipids and blood pressure, decreased plasma MPO and sE-selectin levels and BP values." (PMID 24594096, 2014).